S100B (S100 calcium binding protein B)
Diseases named in the same sentence as S100B in open-access papers (continued):
Sharing a sentence is not in itself a finding about the gene and the disease.
schizophrenia (continued). "Here, the serum levels of S100B in patients diagnosed with schizophrenia was investigated and relationships between age, gender, illness severity, type of medication, treatment time and various metabolic factors, was examined." (PMID 23705829, 2013). "At the protein level, findings suggest that S100B is increased in schizophrenia, and that these protein levels are correlated with medication, gender, age and illness severity." (PMID 23705829, 2013). "The neurotrophic factor, S100B, is released primarily from astrocytes, with serum and CSF levels of S100B reported as altered in schizophrenia." (PMID 23705829, 2013). "More recently, S100B in schizophrenia has been related to glucose metabolism and insulin resistance." (PMID 24358202, 2013). "A correlation analysis showed that levels of S100B increased with BMI in female patients with schizophrenia." (PMID 23705829, 2013). "Here, serum levels of S100B in schizophrenia and influence of age, gender, medication and illness severity were examined." (PMID 23705829, 2013). "Blood levels of S100B levels are increased in schizophrenia, as summarized in a recent meta-analysis of 13 studies involving 420 patients with schizophrenia and 393 control subjects." (PMID 20631894, 2010). "Serum S100B reaches high effect sizes in schizophrenia compared to controls (mean ± SD: 2.02 ± 1.78), as confirmed by including only studies investigating drug-free patients (mean ± SD: 1.94 ± 1.33; n = 7)." (PMID 20631894, 2010). "Alterations are evident in several psychiatric disorders with MI decreases recorded in depressed patients and increases in those with schizophrenia that correlated with increases of S100B." (PMID 20509936, 2010). "Given the increased prevalence of visceral obesity and insulin resistance in schizophrenia, we recently analyzed the relation of serum S100B levels to the BMI and adipose derived hormones in acute paranoid schizophrenia." (PMID 20631894, 2010). "In recent years, there has been a proliferation of interest in the protein S100B, its many physiological roles and its behavior in various neuropathological conditions including mood disorders and schizophrenia." (PMID 20559426, 2010). "Adrenaline, noradrenalin or ACTH-enhanced release of S100B from adipose tissue due to a schizophrenia-related activation of the endocrine stress axis." (PMID 20631894, 2010). "Several studies reported on elevated blood levels of S100B in schizophrenia, which have been attributed to glial pathology." (PMID 20631894, 2010). "A role for S100B has been suggested in the pathogenesis and/or pathophysiology of schizophrenia based on the observation that serum levels of the protein are increased in this psychiatric disorder." (PMID 20827421, 2010). "In conclusion, there is evidence for a novel link between S100B and disturbances of energy metabolism in schizophrenia, resulting in an increased release of S100B from brain and adipose tissue." (PMID 20631894, 2010). "Schizophrenia-related disturbances in adipose tissue metabolism, such as an increased release of S100B, together with triglycerides and free fatty acids due to a predisposition to insulin resistance." (PMID 20631894, 2010). "In summarizing the results of clinical studies, reports consistently show increased S100B levels in patients suffering from schizophrenia in both the acute and chronic psychotic stages of disease." (PMID 19936105, 2009). "They reported that cortical brain regions contained significantly more S100B-immunopositive glia in the schizophrenia group compared to controls." (PMID 19936105, 2009). "The S100B/RAGE axis may also influence white matter integrity and oligodendrocyte function, potentially underlying connectivity deficits characteristic of schizophrenia." (PMID 40650013, 2025). "Similarly, in schizophrenia, elevated S100B levels have been consistently reported in serum and cerebrospinal fluid, reflecting glial dysfunction and ongoing neuroinflammation." (PMID 40650013, 2025).
schizophrenia (continued). "The S100B/RAGE interaction is thought to mediate inflammatory signaling in the brain, contributing to white matter abnormalities, oligodendrocyte loss, and cognitive impairment observed in schizophrenia." (PMID 40650013, 2025). "Levels of P-selectin correlated positively with levels of S100B and IL-6, and it was postulated that in patients with schizophrenia, peripheral immune activation may be related to neuro-inflammation and the activation of astrocytes." (PMID 39858403, 2024). "In addition, the role S100B played in the improvement of schizophrenia through psychotropic drugs, electroconvulsive therapy, and transcranial magnetic stimulation also needs to be studied." (PMID 35743957, 2022). "Our result is consistent with the previous study, which noted postmortem histological study identified that the number of astrocytes was increased in the brain of patients with schizophrenia, and the increased density of S100β+ astrocytes was found in patients with paranoid schizophrenia." (PMID 36232882, 2022). "Schizophrenia patients have higher S100B concentrations than healthy controls." (PMID 35743957, 2022). "In addition, more oligodendrocytes are secreting S100B protein in the white-matter region of the brain in paranoid schizophrenia than in residual schizophrenia." (PMID 35743957, 2022). "In clinical studies, there is controversy as to whether the level of S100B is related to the symptoms of schizophrenia." (PMID 35743957, 2022). "Thus, ethnicity or race should be given serious consideration when studying and interpreting S100B levels in patients with schizophrenia." (PMID 35743957, 2022). "S100B-immunopositive glia was elevated in paranoid as compared to residual schizophrenia patients." (PMID 32116664, 2019). "Concentrations of S100B measured in our individuals were relatively low in all experimental conditions (less than 0.015 ng/ml), but it is assumed that higher values (0.3 ng/ml in patients with schizophrenia) are neurotoxic." (PMID 31644554, 2019). "Increased levels of S100B protein in blood and CSF that can be caused by BBB hyperpermeability and elevated vascular endothelial growth factor (VEGF), a protein known to increase BBB permeability, have been found in patients with schizophrenia." (PMID 30766494, 2018). "In our experiments, both L-AAA and S100β infusion altered neuronal oscillations across frequency ranges commonly thought to support cognitive flexibility, but which are also impaired in many patients with mood disorders or schizophrenia." (PMID 29664924, 2018). "Additionally, sRAGE has been recently suggested to regulate the detrimental effects of S100B observed in the patients with schizophrenia." (PMID 28373983, 2017). "The first finding of this study is that schizophrenia patients have high levels of plasma S100B." (PMID 27279465, 2016). "Although serum S100B might be associated with other conditions such as blood-brain barrier disruption, weight changes or neurological diseases, S100B changes in schizophrenia are lower than would be expected in neurological diseases with brain injury." (PMID 26941608, 2016). "Therefore, our results suggest the possible function of S100B in pathogenesis of schizophrenia, and implicate the important role of autoimmune response and balance to glial dysfunction in patients with schizophrenia." (PMID 27279465, 2016). "Further elimination by title of post-mortem, in vitro, animal and genetic studies, studies investigating S100B in CSF only or studies with patients other than schizophrenia resulted in 38 articles in PubMed, 39 in Web of Science, 21 in Ovid, and 43 in Scopus databases." (PMID 26941608, 2016). "Combined with the correllation between plasma level of S100B and IL-17 we found, this study help to bridge the gap between glial damage and immune dysfunction, especially the autoimmune imbalance hypotheses of schizophrenia." (PMID 27279465, 2016).
schizophrenia (continued). "Based on previous studies, we hypothesized higher S100B in schizophrenia when compared to healthy controls." (PMID 26941608, 2016). "Considering the range of measured S100B concentrations, massive glial or neuronal destruction is unlikely to be the cause of S100B increase in schizophrenia." (PMID 27013967, 2016). "Our comprehensive meta-analysis, including 19 original studies with 766 patients and 607 healthy control subjects revealed elevated levels of the glial marker protein S100B in serum in schizophrenia, which is related to illness duration and to clinical symptomatology." (PMID 26941608, 2016). "The relative increase of serum S100B levels in the course of schizophrenia could be explained with dynamic glial alterations in the course of the disease." (PMID 26941608, 2016). "Earlier Studies have consistently reported increased S100B levels in schizophrenia." (PMID 27013967, 2016). "Although S100B could be regarded as a possible biomarker of schizophrenia, limitations should be accounted when interpreting results, especially because of the high heterogeneity that remained >70%, even after carrying out subgroups analyses." (PMID 25202915, 2014). "The question has emerged if S100B is a specific marker for astrocyte dysfunction in schizophrenia?" (PMID 23705829, 2013). "In addition, polymorphisms in the receptor for S100B, RAGE (receptor for advanced glycation end products) have been linked with schizophrenia, as have increased levels of the soluble version of RAGE." (PMID 23705829, 2013). "Serum S100B levels were measured in patients with schizophrenia treated with clozapine." (PMID 23705829, 2013). "Previous studies have focused on the role of S100B in astrocytes, and suggested that astrocyte dysfunction may increase release of S100B in schizophrenia." (PMID 23705829, 2013). "Importantly, the data here showed that S100B levels were elevated in female patients with schizophrenia compared to male patients and to those female and male healthy control subjects." (PMID 23705829, 2013). "While it may be possible that our findings are explained, in part, by pathogenetic mechanisms, further studies would be required to determine this possibility, for example by investigating the levels of S100B in siblings of patients with schizophrenia." (PMID 23705829, 2013). "In schizophrenia, brain, CSF and serum S100B levels are elevated." (PMID 23547920, 2013). "In this current study we also did not investigate if the levels of S100B were associated with genetic mutations reported in schizophrenia." (PMID 23705829, 2013). "Interestingly, molecular links between S100B, DA2Rs and schizophrenia have been suggested where S100B has been shown to interact with the third cytoplasmic loop of the DA2R, and to enhance receptor signalling to ERK and inhibition of adenylate cyclase." (PMID 23705829, 2013). "Of interest, overweight, visceral obesity and insulin resistance may be correlated with levels of S100B in schizophrenia." (PMID 23705829, 2013). "Moreover, recent work raises the possibility that release of S100B from adipocytes contributes significantly to the elevated serum S100B levels found in schizophrenia." (PMID 20827421, 2010). "Although there is suggestion that variants within the S100B gene predispose to a psychotic subtype of bipolar affective disorder, possibly via alteration of gene expression, conclusions about the role of S100B in the pathogenesis/pathophysiology of schizophrenia should await more detailed analyses." (PMID 20827421, 2010). "Abdominal Obesity: We did not measure waist circumferences in this study, but blood concentrations of MCP-1 were elevated in the schizophrenia group (P = .034), indicating an increased visceral fat mass, and correlating with levels of S100B (r = 0.673, P = .023)." (PMID 20631894, 2010).
schizophrenia (continued). "Over production of S100B (micromolar levels) can be toxic and follow brain-damage resulting from stroke and ischemia and accompany severe mental disorders such as schizophrenia, bipolar disorder, depression, Alzheimer's disease, Down's syndrome, phenylketonuria and cerebral palsy." (PMID 20509936, 2010). "Elevated blood levels of S100B in schizophrenia have so far been mainly attributed to glial pathology, as S100B is produced by astro- and oligodendroglial cells and is thought to act as a neurotrophic factor with effects on synaptogenesis, dopaminergic and glutamatergic neutrotransmission." (PMID 20631894, 2010). "Therefore, altered S100B protein expression in schizophrenia probably indicates systemic disturbances in cellular energy supply (e.g., by disrupted peripheral and cerebral insulin signaling) rather than adipocyte- or glia-specific pathologies." (PMID 20631894, 2010). "In the context of this recently identified framework of metabolic disturbances accompanying S100B elevation in schizophrenia, it rather has to be attributed to systemic alterations in glucose metabolism than to be considered a surrogate marker for astrocyte-specific pathologies." (PMID 20631894, 2010). "It remains unclear whether S100B may be considered as a predictor of metabolic syndrome in schizophrenia." (PMID 20631894, 2010). "As reviewed in this paper, our recent studies suggest that overweight, visceral obesity, and peripheral/cerebral insulin resistance may be pivotal for at least part of the elevated S100B serum levels in schizophrenia." (PMID 20631894, 2010). "Overexpression of S100B is observed in various conditions, including Down syndrome, Alzheimer’s disease, epilepsy, Parkinson’s disease, multiple sclerosis, schizophrenia, cerebral palsy, Creutzfeldt–Jakob disease, autism spectrum disorder, and also in COVID-19." (PMID 39519343, 2024). "Due to the absence of association between serum S100B and brain structure in the current study’s patient group (also after correction for current AP use), we are unable to make any deductions about S100B’s cerebral actions in schizophrenia." (PMID 28358925, 2017). "Based on these, we speculate that the -374T/A polymorphism alters the RAGE-S100B interaction leading to the alteration of the S100B level via influencing the transcriptional activity of the RAGE gene and thus affecting the positive symptoms of schizophrenia." (PMID 28373983, 2017). "In contrast to antidepressant drugs, where S100B serum levels have been discussed as indicators/biomarkers for successful treatment, as of yet there is no meta-analytic evidence for serum S100B being related to treatment success of neuroleptics/antipsychotics in schizophrenia." (PMID 26941608, 2016). "Hence, S100B might also be directly involved in processes leading to structural white matter changes in schizophrenia." (PMID 27013967, 2016). "Therefore, further studies about S100B and inflammatory markers in schizophrenia and other psychiatric disorders from large-scale populations and strictly control of confounding variables are necessary to elucidate the role of S100B and inflammatory markers in schizophrenia, and values of biomarker." (PMID 27279465, 2016). "Therefore, our result of high level of plasma S100B in schizophrenia patients reinforces the glial dysfunction and brain damages hypothesis in the pathogenesis of schizophrenia." (PMID 27279465, 2016). "S100B secretion is increased by pro-inflammatory cytokines and this protein could be involved in the imbalanced inflammatory response observed in several brain disorders, including Alzheimer's disease, major depression and schizophrenia." (PMID 25202915, 2014). "However, contradictory to the hypothesis that astrocyte derived S100B levels are raised in schizophrenia, is the finding that chronic antipsychotic medication, such as haloperidol or olanzapine, reduce astrocyte numbers in Macaque Monkeys." (PMID 23705829, 2013).
schizophrenia (continued). "Of interest, S100B is also expressed in immune cells (including T cells and natural killer cells) and in adipocytes suggesting it may have a role in altered immune response and metabolic activity in schizophrenia." (PMID 23705829, 2013). "Indeed, findings have suggested that altered S100B levels in schizophrenia may be due to metabolic disorder, visceral obesity, diabetes and/or immune dysfunction in this illness." (PMID 23705829, 2013). "Histological findings indicate that glial activation may result in increased intracellular S100B in paranoid schizophrenia (positive symptoms), whereas white matter damage or dysfunction in residual schizophrenia (negative symptoms) may lead to extracellular release." (PMID 24358202, 2013). "Therefore, it remains unclear if serum levels of S100B are reflecting blood-brain barrier integrity also in schizophrenia." (PMID 20631894, 2010). "Not only did it achieve positive results in the improvement of psychological symptoms and cognitive functions, but it also provided new insights into the biological mechanism of schizophrenia by regulating serum BDNF and S100B levels." (PMID 41312344, 2025). "The psychotic symptoms, severity of schizophrenia symptoms, memory ability, cognitive function, serum BDNF, S100B, and GFAP levels, and incidence of adverse reactions between the two groups were compared." (PMID 41312344, 2025). "Increasingly, the S100B/RAGE axis is recognized as both a mechanistic driver and a promising biomarker in AD and schizophrenia." (PMID 40650013, 2025). "It has been shown that S100B correlates with the extent of trauma, survival, and neurological parameters, and increased expression of this protein in the blood serum of patients with acute exacerbations and deficit symptoms in schizophrenia may lead to a progressive reduction in neuropil." (PMID 39519343, 2024). "Another study discovered that cerebrospinal fluid S100B levels showed a positive correlation with PANSS total, positive, and general scores in patients with schizophrenia." (PMID 35743957, 2022). "It has previously been demonstrated that patients with schizophrenia have lower serum BDNF, MBP, and GFAP levels, but higher serum IL-6 and S100B." (PMID 34025476, 2021). "We also investigated markers of inflammatory response (C-reactive protein, IL-2, IL-6, IL-10), the activity of leukocytic elastase (LE) and α1-proteinase inhibitor (a1-PI), antibodies to S100B and myelin basic protein (MBP) in schizophrenia." (PMID 34025476, 2021). "CSF S100B level showed a positive correlation with PANSS total, positive, and general scores in patients with schizophrenia." (PMID 32439851, 2020). "In humans, S100B may induce plasticity effects in the brain, and an imaging study demonstrated a high S100B expression in human corpus callosum, so opening new perspectives for future studies investigating schizophrenia and other major neuropsychiatric disorders." (PMID 25202915, 2014). "Taken together, these studies support the S100B/DA2R protein complex as a molecular target for antipsychotic medications and possible aberrant S100B/DA2R-mediated signalling in schizophrenia." (PMID 23705829, 2013). "In conclusion, non-convulsive electroconvulsive therapy combined with drug therapy has a significant effect in the therapy of schizophrenia, which can effectively improve psychiatric symptoms and cognitive function of patients, regulate serum BDNF and S100B levels, and is safe." (PMID 41312344, 2025). "While S100B is not specific to schizophrenia, its persistent elevation underscores its value as a peripheral biomarker for glial dysfunction and disorder activity." (PMID 40650013, 2025). "Studies based on serum and cerebrospinal fluid biomarkers entail invasive procedures, rendering them less practical for schizophrenia patients, and markers like QAlb and S100b are non-specific, incapable of precisely mirroring BBB permeability changes." (PMID 39940642, 2025).